Y_RNA (Y RNA )
Gene: Miscellaneous RNA gene on chromosome 7 (75,353,885 to 75,353,986, reverse strand). Ensembl gene ENSG00000199870.
Homologues: Orthologues: chimpanzee Y_RNA (99% identical), pig Y_RNA (75% identical). Paralogues in human: Y_RNA (100% identical), Y_RNA (97% identical), Y_RNA (93% identical), Y_RNA (92% identical), Y_RNA (90% identical), Y_RNA (89% identical), Y_RNA (87% identical), Y_RNA (85% identical), RNY3 (84% identical), RNY3P12 (84% identical), Y_RNA (84% identical), RNY3P1 (83% identical), and 98 more.